FN1 (fibronectin 1)
Diseases named in the same sentence as FN1 in open-access papers (continued):
Sharing a sentence is not in itself a finding about the gene and the disease.
cancer (continued). "A study also reported that the suppression of LTBP1 can attenuate cancer-associated fibroblast (CAF) transformation and inhibit FN1 in ESCC." (PMID 34456964, 2021). "In fact, down-regulation of fibronectin-1 in blastuloid spheroids, is consistent with its well-established role in driving migration of cancer cells." (PMID 34376568, 2021). "The four genes are associated with important cancer pathways, namely, the MAPK/PI3K pathways (FN1 and DUSP4), the Wnt pathway (LEF1), and the TGF pathway (SMAD9)." (PMID 34485158, 2021). "MiR-200c inhibits the expression of FNI, significantly reduces cell proliferation, and inhibits migration and invasion, suggesting that the expression of FN1 is a good indicator of the state of cancer cells." (PMID 34276798, 2021). "Cancer prognosis studies demonstrate that the higher the level of fibronectin 1 in vivo, the worse the prognosis and survival rate." (PMID 33728331, 2021). "Accumulating evidence shows that pathways related to FN1 axis are promising therapeutic targets in cancer treatment." (PMID 33731188, 2021). "The analysis of UALCAN demonstrated that FN1 was significantly hypermethylated in HNSCC tissues compared with normal para-carcinoma tissues." (PMID 34746236, 2021). "Some of the crucial genes in this overlap include VEGFA, PDGFC and FN1 that were known to be involved in angiogenesis in different types of cancers." (PMID 32720467, 2020). "Kaplan–Meier curves show the association between gene expression and cancer survival, data indicate that patients with high expression of ITGA5 and FN1 exhibit lower survival, while the low expression of PLAC8 is associated with shorter survival." (PMID 32848147, 2020). "Target identification assay showed that miR-1 directly regulates fibronectin 1 (FN1), which has cancer metastasis related functions." (PMID 32456271, 2020). "CM from both cancer cell lines induced mRNAs encoding the M2 markers CD163, FN1, and IL10 in ShCtrl THP-1 cells; the induction ranged from 2- to 4-fold by CM from MCF-7 cells, and from 5- to 60-fold by CM from MDA-MB-231 cells." (PMID 33086476, 2020). "Fibronectin (FN1) is an extracellular matrix protein gaining increasing attention for its multifaceted roles in cancer progression." (PMID 32630254, 2020). "FN1 seems to be associated with cisplatin resistance and over-expression of CDH3 correlates to a poor prognosis in carcinomas of the breast, prostate, ovary, colon and stomach." (PMID 33086649, 2020). "Overall (with exceptions), the 3 upregulated genes (PLAU1, FN1 and CDCA5) were generally associated with poor prognosis in these cancer types when gene expression levels were upregulated." (PMID 31443700, 2019). "Fibronectin 1 (FN1) is found in 64% of patient combinations belonging to all nine cancer types analyzed." (PMID 31695721, 2019). "During this PFC we detected an up-regulation of the FN1 mRNA, which indicates a cancer type-specific reaction to μg." (PMID 31261642, 2019). "Others, such as FN1, EP300, CASP8, EGF and MAP2K1, which were associated with the pathways involved in cancer, were also hub-node genes." (PMID 31501464, 2019). "In accordance with our findings, expression data from The Cancer Cell Line Encyclopedia show that ~82% of the OC-derived cell lines reproduce the same phenomenon for FN1, FAM129A, and CD97 genes." (PMID 31406110, 2019). "To this aim, we considered the Proteoglycans in cancer pathway (see Run-time analysis), in which we perturbed the mean level of the fibronectin 1 gene (FN1) that appears to be the most connected node (80 neighbours)." (PMID 31652275, 2019). "In contrast, hybMENA11a-positive tumors express essentially a low FN1 level in the stroma, in agreement with the proteomic data obtained for cancer cell lines." (PMID 29907768, 2018). "Other genes like CCNE1, SENP5, FN1, KMT2B, and DUX4 were alsoidentified by HGT-ID; these genes were previously reported to be associated with tumorigenesis or cancer invasion." (PMID 30016933, 2018).
cancer (continued). "They used four established EMT markers—CDH1 (epithelial marker, E type), CDH2 (mesenchymal marker, M type), VIM (M type), and FN1 (M type)—as seeds to develop a pan-cancer EMT signature on the basis of TCGA pan-cancer RNA-Seq data." (PMID 29426364, 2018). "Measuring the level of FN1 in other cancers would be helpful to ensure that this target is specific solely for HCC." (PMID 28842594, 2017). "Possibly, like in some other cancer cells, FN1 induced specific matrix metalloproteinases expression, such as MMP9/MMP2, to promote invasion and metastasis." (PMID 28147311, 2017). "The EDB exon of the FN1 gene, whose inclusion was preferred in six different cancer types, was previously found to be highly expressed in HNSC, COAD and LIHC." (PMID 25908786, 2015). "FN1 encodes fibronectin, a glycoprotein in extracellular matrix (ECM), which has been implicated in the development of many types of cancer." (PMID 26422603, 2015). "Some of the common cancer-regulated alternative splicing events we identified in genes such as FN1, FBLN2, AP2B1 and TCF20 are most likely oncogenic drivers." (PMID 25908786, 2015). "It has been indicated that FN1 is involved in various aspects of cancer-related biological processes, such as cellular adhesion and migration." (PMID 24765172, 2014). "For the third pair of samples where FN1 integration was found in the cancer tissue only, the expression of FN1 was increased in the cancer tissue." (PMID 23236287, 2012). "The serum concentration of Fibronectin 1 was higher in cancer patients (mean: 190, min: 11, max: 326 μg ml−1) compared with normal volunteers (mean: 125, min: 58, max: 212 μg ml−1) (P<0.001)." (PMID 20068563, 2010). "At least 50 genes in our list are already known to be regulated by DNA methylation, such as those encoding cancer antigens (a set of MAGE and GAGE), H19, S100A4, IGFBP4, UCHL1, COL1A2, CLU, FN1, and TGFBI." (PMID 19234609, 2009). "Among these genes, the most overexpressed in platelet-educated cancer cells are those encoding proteins involved in cancer progression and metastasis, including SERPINE1 (358%), MMP2 (297%), MMP10 (214%), TIMP1 (187%), FN1 (166%), TMPRSS4 (146%) and RHOC (102%)." (PMID 40096084, 2025). "Thus, our findings indicate that CPLF top-weighted genes regulate FN1 expression in myofibroblasts, potentially enhancing cancer cell growth." (PMID 41405822, 2025). "The effective communication between C3 FN1+ TCs and immune cells highlighted their ability to employ immune evasion strategies, which might enhance cancer survival and dissemination." (PMID 40612060, 2025). "Finally, FN1 can, for example, activate the integrins α5β1 and α4β1, which increase the ability of cancer cells to transport drugs like doxorubicin out of the cytoplasm via the drug transporter ABCC1." (PMID 40096084, 2025). "Differential gene expression analysis showed overexpression of classic epithelial genes (e.g., SFTPC and STEAP1), genes associated with cancer (e.g., CLDN6), and regulators of EMT (e.g., vimentin, fibronectin 1, and N-cadherin) in Oncopig LC versus normal pig lung tissues." (PMID 39975891, 2025). "Specifically, it would be interesting to examine whether there are changes in the carbohydrate motifs of FN1 after the interaction between cancer cells and platelets." (PMID 40096084, 2025). "We therefore turned our attention to the effects of overexpressing FN1 on cancer cells." (PMID 40096084, 2025). "We found that prioritized ligands with a high impact on cancer gene expression, including Fn1, Mmp9, and Cd274, were mainly expressed in myeloid cells, suggesting that the molecular changes of cancer cells may be induced by myeloid cells." (PMID 38169569, 2024).
cancer (continued). "In inverse co-culture at both time points and standard co-culture at 72 h 26 genes were mutually expressed, among them genes of the KEGG pathway Proteoglycans in cancer, like Fibronectin 1 (FN1), Hepatocyte Growth Factor (HGF), Epiregulin (EREG) and Tissue Inhibitor of Metalloproteinases 1 (TIMP1)." (PMID 39098880, 2024). "Indeed, both COL1A1 and FN1 have been identified as individual prognostic biomarkers in a variety of cancers." (PMID 38791926, 2024). "Our findings identify a shift in FN1 isoform expression upon THUMPD3 depletion that favours production of an FN1 variant lacking the pro-angiogenic Extra Domain B (EDB), which has been previously associated with cancer progression." (PMID 39656728, 2024). "Additionally, MSC-2 shown high expression of cancer-associated fibroblast (CAFs) markers, including FAP, FN1, and CD44." (PMID 38281962, 2024). "FN1, a member of the glycoprotein family in the extracellular matrix, has been reported to regulate a variety of biological processes, including cell adhesion, migration and cell movement, in various malignant tumors." (PMID 39218967, 2024). "We integrated analyzed the function of P4HA3 among 33 types of cancers, and found that P4HA3 was associated with proliferation markers (PCNA and MKI67), EMT markers (VIM, TWIST1, SNAI1, SNAI2, FN1 and CDH2), extracellular matrix (ECM) markers (MMP9, MMP7, MMP2 and MMP14)." (PMID 39504328, 2024). "Studies have provided valuable insights into the diverse role of FN1 in different cancer types." (PMID 38913913, 2024). "Through this study’s simple analysis, We can tentatively speculate that the overexpression of COL10A1/FAP/FN1 is positively correlated with cancer immunity." (PMID 38063927, 2023). "This second cluster could represent a cancer-associated fibroblast (CAF) population characterized by low expression of MSLN and WT1 and high expression of ACTA2, S100A4, COL5A2, SPARC, and FN1." (PMID 36901697, 2023). "Firstly, by examining the expression levels of the COL10A1/FAP/FN1, we can sensitively detect whether COVID-19 infection is promoting cancer progression." (PMID 38063927, 2023). "Fibronectin 1 (FN1), which is highly expressed by GGN macrophages, could form complexes with integrin subunits of other cells (FN1_α2β1 complex, FN1_α3β1 complex, FN1_α4β1 complex, FN1_α5β1 complex), which promoted cancer cell migration through adhesion." (PMID 37745301, 2023). "In addition, this protein-protein interaction network includes CRP, FN1 and PLAU, implicated in different ways with cancer risk or progression." (PMID 36649303, 2023). "Furthermore, FN1 has been shown to promote cell proliferation and migration in cancers such as esophageal, oral, nasopharyngeal, colorectal, ovarian, renal, and thyroid." (PMID 37607964, 2023). "FN1 is a glycoprotein present in the extracellular matrix, as well as on the cell surface that stimulates cell adhesion along with migration, both of which are important in the onset and progress of cancer." (PMID 36059672, 2022). "Importantly, Hsp90ab1 immuno-precipitated latent TGFβ and inactivated TGFβ, whereas MSN interacted with CD44, a cancer stem-cell marker, as well as fibronectin 1, an ECM protein." (PMID 34976221, 2022). "Previous studies have shown that FN1 could promote cancer cell metastasis, angiogenesis and proliferation." (PMID 35197128, 2022). "Hence, we analyzed TCGA expression data from 32 cancer types (∼9,000 patient samples) to identify LncRNAs associated with EMT markers, VIM, FN1, SNAI1, SNAI2, and CDH1 (and material and method)." (PMID 36120580, 2022). "In HCC, cancer cell-based fibronectin 1 (FN-1) activates glycolysis within macrophages by triggering TLR4, which results in the significant upregulation of pyruvate kinase M2 (PKM2), which, in turn, enhances the syntheses of IL-1β, IL-12p70, TNF-α, HLA-DR, and PD-L1." (PMID 36588722, 2022). "Meanwhile, FN1 has been connected to cancer patients’ prognosis and treatment responsiveness." (PMID 36081567, 2022).
cancer (continued). "FN1 was found to be a marker for epithelial-mesenchymal transition-driven cancer stemness." (PMID 35477343, 2022). "Through CellphoneDB, we found that cancer cells were relatively likely to interact with stromal cells, and the significantly enriched ligand‒receptor pairs included FN1, collagen, and the TGFβ family." (PMID 36127333, 2022). "FN1 could exert its function in different biological processes, and it could promote carcinogenesis in many cancers." (PMID 35197128, 2022). "Downregulation of FN1 could increase the expression of the proapoptotic protein Bax and decrease the expression of the antiapoptotic protein Bcl-2 in cancer cells." (PMID 35370699, 2022). "In this regard, it has been recently demonstrated that in colon cancer, stromal HSF1 drives the transcription of genes encoding matrix proteins (FN1, LAMA1), matrix enzymes (MMP7, MMP9), and matrix chaperones (SERPINH1/Hsp47), inducing ECM remodeling and leading to cancer progression." (PMID 34198675, 2021). "Finally, the potential employment of FN1 as a useful biomarker and valuable target for clinical applications, including cancer diagnosis and therapy is debated." (PMID 33731188, 2021). "Besides being upregulated during EMT, FN1 plays important roles during subsequent adhesion of cancer cells to endothelial cells." (PMID 34641959, 2021). "Additionally, there was a significant increase in FN1 expression in stage III cancer compared with lower FIGO stage cancers (stages I and II)." (PMID 34093898, 2021). "TNF-α expression was observed to upregulate expression of several cancer-associated genes in the epithelial cells which include extracellular matrix (ECM) remodeling genes such as MMP9, PLAU, FN1 and ICAM1, chemokines such as CCL2, CXCL2, CXCL3 and CXCL10 and regulatory genes such as UBD and PTGS2." (PMID 34946170, 2021). "In conclusion, considering that EVs are stable in the blood representing a non-invasive source for monitoring cancer disease, the FN1-enriched EVs may represent new prognostic and theranostic markers in the clinical management of cancer." (PMID 33731188, 2021). "The results revealed that among differentially expressed proteins, FN1 is over-expressed on cancer cells-derived EVs and may be a suitable, specific and sensitive diagnostic biomarker for NSCLC." (PMID 33731188, 2021). "Therefore, FN1 is a potentially useful biomarker and target for several clinical applications, including cancer diagnosis and therapy." (PMID 33731188, 2021). "In this process, integrins mediate the binding with and the turnover of FN1 suggesting that FN1 may facilitate or mediate EV uptake through the same machinery, as has been demonstrated in cancer cell systems." (PMID 33816490, 2021). "SPARC expression in cancer cells enhanced their migration and invasion on FN1-coated dishes." (PMID 33579227, 2021). "Fibronectin 1 can bind to cancer cells and favors metastasis and invasion." (PMID 33728331, 2021). "After cancer treatment, if fibronectin 1 levels are still high, the prognosis is poor." (PMID 33728331, 2021). "In addition, six tumor suppressor genes previously implicated in cancer (BTK, CHD1, FN1, NFATC2, NOTCH1, and NRP1) were found in at least two samples." (PMID 34489456, 2021). "As a critical ECM component, FN1 is overexpressed in multiple cancer types." (PMID 32756405, 2020). "Moreover, the p62 protein was mainly localized in the cytoplasm, and the phenomenon of colocalization with FN1 indicated that oncofoetal FN1 was indeed present in the cytoplasm of cancer cells." (PMID 33318468, 2020). "Collectively, these meta-analyses suggest that in a given tissue, aggregated expression of FN1, TGFBR2, TGFB2, and TGFBI might serve as an index for the extent of cancer-associated fibroblasts (CAFs)." (PMID 32605311, 2020). "LTBP1 was mainly observed in cancer cells while FN1 was mainly observed in the surrounding stroma." (PMID 32216815, 2020).
cancer (continued). "Moreover, elucidation of these two novel pathways allows for a better understanding of how FN1 works and how their dysregulation can potentially contribute to a poorer prognosis and metastatic spread in cancer patients." (PMID 32630254, 2020). "On the contrary, evidence suggests that FN1 level was increased in many types of cancer." (PMID 32971853, 2020). "In the future, we aim to investigate whether we can inhibit the expression of FN1 by interfering with autophagy to control the progression of cancer." (PMID 33318468, 2020). "let-7g reduces the motility of cancer cells such that basal SOC might be insufficient to support FN1 expression and MAPK pathway activation." (PMID 30959863, 2019). "FN1 is a novel protein involved in regulating cancer progression." (PMID 31850052, 2019). "In several cancers, FN1 is a key mediator of disease progression and metastasis." (PMID 29484116, 2018). "MMP9, FN1, FGF13, and COL4A2 are significant genes in the pathways associated with cancer." (PMID 28191466, 2017). "In the present study, MMP9 and FN1, key proteins in cancer pathways, were also upregulated." (PMID 28191466, 2017). "In one, a mechanism identified in cancer cells to resist infection by herpes viruses was decreased FN1 expression, which may have reduce viral attachment." (PMID 27901484, 2017). "We also found elevated fibronectin (FN1) transcript in CD11b+ cells of cancer patients." (PMID 26840567, 2016). "FN1 has been suggested as a potential biomarker in various cancers." (PMID 27684953, 2016). "In addition, FN1 network neighbors are enriched for a well-known cancer signaling pathway, the PI3K-Akt signaling pathway (KEGG pathway, P = 1.81e-14)." (PMID 27333808, 2016). "We selected Fibronectin (FN-1), a gene involved in wound healing, blood coagulation, and cancer metastasis, as a representative candidate that showed significantly different expression in hemangiosarcoma and splenic hematoma, but did not meet the initial FDR criteria." (PMID 21062482, 2010). "However, cell spreading on collagen was slower than spreading on FN (1–2 h), confirming the differential effect matrix had on cancer cell motility." (PMID 19626122, 2009). "Moreover, our epithelial-to-mesenchymal transition (EMT) analysis revealed a consistent inverse association between PEBP1/STK11 co-expression and EMT marker genes, including SNAI1, SNAI2, FOXC2, ZEB1, and FN1, across most cancer types examined, thus underscoring a uniform anti-EMT signature." (PMID 40806276, 2025). "However, while treatment of luminal cancer cell lines with recombinant TGFβ (rTGFβ) increased FN1 and COL1A1 expression, the magnitude of the effect was smaller, and a longer treatment was needed in cells with high endogenous ThPOK levels (T47D), compared to cells with lower levels (MCF7)." (PMID 41231242, 2025). "Additionally, higher FN1 expression was found in patients with higher FIGO stages of cancer." (PMID 34093898, 2021). "Therefore, fibronectin 1 is also an important indicator of cancer prognosis." (PMID 33728331, 2021). "Upregulation of FN1 may depend on miR-9-3p downregulation in cancer cells." (PMID 34943943, 2021). "Additionally, in some cancer types, upregulated expression of fibrous proteins such as collagen and fibronectin-1 was reported, indicating stroma proteins could serve as a barrier against drug diffusion." (PMID 32796757, 2020). "Interestingly, upregulation of FN1 has been observed in a variety of cancers." (PMID 32630254, 2020). "Interestingly, FN1 is overexpressed in a variety of cancers." (PMID 32630254, 2020). "Furthermore, FN1 was found to be correlated with the drug-resistance of cancer cells." (PMID 25824986, 2015). "Fibronectin 1 (FN1), a core component of the ECM, has been reported in various cancers to activate the PI3K/AKT and FAK pathways through integrin receptors, promoting cell migration, invasion, and chemotherapy resistance." (PMID 40678072, 2025).